IL1B (interleukin 1 beta)
Diseases named in the same sentence as IL1B in open-access papers (continued):
Sharing a sentence is not in itself a finding about the gene and the disease.
tumor (continued). "Breast and gastric tumor-derived exosomes can induce a M1 pro-inflammatory response in macrophages through the activation of NFκB, which in turn stimulates production of inflammatory cytokines including GCSF, IL-6, IL-8, IL-1β, CCL2, and TNF-α." (PMID 31555295, 2019). "Inflammatory cytokines, for example, interleukin-1 beta (IL-1β) and tumor necrosis factor alpha (TNF-α) secreted by immune cells could be acting as chemoattractants for MSCs chemotaxis to tumor sites." (PMID 31130595, 2019). "Similar results were observed following IL-1β stimulation, demonstrating that 7-h stimulation, but not 15-min stimulation by IL-1β has led to Notch1 activation in the tumor cells, but not in the MSCs." (PMID 31105691, 2019). "Upon binding to IL-1R1, IL-1β increases the expression of VEGF and its receptors on endothelial cells (ECs), while activation of p38-MAPK signaling results in the migration of ECs and tube formation, both contributing to tumor angiogenesis." (PMID 31500658, 2019). "Considering that the IL-1β/G-CSF inflammatory axis might be involved in the increased propensity for NET formation, we treated the tumor-bearing mice with the commercially available, selective inhibitor of IL-1R, anakinra." (PMID 31552036, 2019). "IL1A and IL1B were found to be significantly increased in tumors (b p < 0.0001 and p = 0.003, respectively) compared to normal samples while IL1RN (IL-1RA) was significantly decreased in tumor versus normal tumors (p = 0.02)." (PMID 31346466, 2019). "Besides direct effects of IL-1β and products of its target genes on the expansion of the MDSC pool, IL-1β induced CC-chemokine ligand 2 (CCL2) in macrophages and tumor cells." (PMID 30042333, 2018). "Moreover, IL-1β, acting together with vascular endothelial growth factor (VEGF), appeared to be a major mediator in the tumor microenvironment and plays a crucial role in mounting and maintaining tumor-mediated angiogenesis." (PMID 29364159, 2018). "In the tumor tissue, we also observed changed expressions of cytokines, considered to be involved in antitumor immune response; IFN-γ enhanced secretion, but decreased IL-1β expression after treatment with calcitriol and its analogs." (PMID 30037009, 2018). "On the other hand, EOC cells can stimulate the activation of CAFs by producing high levels of interleukin-1β (IL-1β) and TGF-β, which subsequently induces secretion of IL-8, IL-6, IL-1β, VEGF, and growth regulated oncogene-alpha (GRO-α) by CAFs to promote tumor progression." (PMID 30042343, 2018). "Therefore, BRAFV600E inhibitors in a cell type- or microenvironment-specific manner inhibit (tumor) and promote (APC) IL-1β secretion." (PMID 29983861, 2018). "Other upregulated genes such as PTEN, ZEB2, STAT3 and IL1B did not align with tumour expression pattern as they are consistently downregulated in the patients datasets." (PMID 30176945, 2018). "A reduction of local tumours or lung metastasis was found in mice lacking functional IL-1R signalling (IL-1B KO), together with diminished tumour angiogenesis." (PMID 29760166, 2018). "The inhibition of IL-1β by I3C and DIM may lead to the attenuation of tumor angiogenesis and protection against carcinogenesis but warrants further investigation." (PMID 29364159, 2018). "To identify the MPE effectors and transcriptional signatures of IL-1β/KRAS/IKKα-addicted tumor cells, we subjected KRAS-silenced, IKKα-silenced, and IL-1β-challenged LLC and MC38 cells to microarray analyses, seeking for transcripts altered heterodirectionally by silencing/challenge." (PMID 29445180, 2018). "However, considering the other markers, such as IL-1β, IL-12, CD86 etc., tested using q-PCR, ELISA and flow cytometry, we confirmed that as a whole Ndrg2−/− macrophages tended to have an M1–like tumor-suppressor phenotype compared with WT macrophages." (PMID 29445150, 2018).
tumor (continued). "The key mechanisms by which IL-1β promotes tumor development are driving chronic non-resolved inflammation, endothelial cell activation, tumor angiogenesis and induction of immunosuppressive cells." (PMID 30042333, 2018). "Given that both IL-1β and IL-8 are known to promote angiogenesis, the inhibitory effect of I3C and DIM on these two cytokines would suggest a regulatory effect of I3C and DIM on the tumor environment that involves angiogenesis." (PMID 29364159, 2018). "Conversely, in THP-1 cells, the decrease in TNF-α, IL-6 and IL-1β levels by WRE may prevent excessive activation of NF-κB, diminish cytokine induced tumour immunosuppressive activity and cancer progression." (PMID 29631586, 2018). "Some studies have shown that IL-1β could induce upregulation of CXC chemokine receptor 3 (CXCR3) in T cells and tumor cells." (PMID 30359318, 2018). "However, it was found in another study that stimulation of the monocytic cell line THP1 with tumor-exosomes induced TNF-α, IL-1β, and IL-6 through TLR2 and TLR4 signaling." (PMID 29867942, 2018). "IL-1β induces COX2 expression in PDAC cells, suggesting the potential for a positive feedback loop to further increase PGE2 secretion within the TME, and increases tumor fibrosis." (PMID 30383833, 2018). "Importantly, the GLPS and triterpene acid were demonstrated to promote the production of cytokines, such as IL-1β, IL-4, IL-6, IL-12, IL-17, RANTES, TNF-α and IFN-γ, and thus to exhibit immuno-modulation and anti-tumor activities." (PMID 30139984, 2018). "Although there is extensive evidence in the literature demonstrating that IL-1β promotes tumor invasiveness and angiogenesis in vivo, direct evidence for the relation between IL-1β levels and tumor progression have not been found." (PMID 30586442, 2018). "ATP released by dying tumor cells functions as a “find me” signal attracting myeloid cells, including DC, to the tumor bed via binding to the purinergic receptor, P2X7, on DC and stimulating NLRP3 inflammasome activation and the proteolytic maturation of IL-1β." (PMID 29462947, 2018). "Further work has shown that cytokines play a role in the regulation of complement inhibitory protein expression, and in particular, IFN-γ, TNF-α, IL-1β (IL1B), and TGF-β (TGFB) have been found to upregulate complement regulatory proteins in cultured tumor cells." (PMID 30473747, 2018). "IL-1β, IL-6 and RANK Ligand also amplify inflammation and promote tumor growth and dissemination." (PMID 30038719, 2018). "Similarly, the level of IL-1β, IL-6 and TNF-α was also increased by APS in EAC tumor-bearing mice in vivo." (PMID 28303957, 2017). "Not only does IL-1B appear positively correlated with MAP17 in all tumors, other interleukins including IL-15, IL-18, IL-1A, IL-32 and IL-7 and interleukin receptors including IL-10RB, IL-17RC and IL-2RG appear in at least three of the tumor types." (PMID 29228712, 2017). "IL1-β also regulates HIF-1α protein, involving an inflammatory signaling pathway to NF-ĸB and COX-2, resulting in the upregulation of VEGF (vascular endothelial growth factor), a potent angiogenic factor needed for metastasis and for tumor growth." (PMID 28785138, 2017). "Tumor-bearing mice neither showed elevated serum levels of the inflammatory cytokines IL-6 and IL-1β, known activators of hepcidin expression nor increased hepatic hepcidin mRNA levels (Hamp1)." (PMID 29167669, 2017). "Although all six types of macrophages showed increased phagocytosis of tumor cells in the presence of TTI-621, M(-), M(IL-4) and M(HAGG+IL-1β) macrophages exhibited slightly lower phagocytic capabilities compared to the M(IFN-γ), M(IFN-γ + LPS) and M(IL-10 + TGFβ) subsets." (PMID 29084248, 2017). "Recent data indicate that endocrine dysfunction in patients with MG may be related to the production of growth factors as well as of cytokines such as IGFBP-2 and IGFBP-3, VEGF, IL-1β, IL-6, and TNF-α by tumor cells or their microenvironment." (PMID 28740334, 2017).
tumor (continued). "However, several studies have shown that EBV infection can induce the NLRP3 inflammasome to produce IL-1β and IL-18, leading to the growth and activation of anti-apoptosis mechanisms of EBV-infected tumor cells." (PMID 28732079, 2017). "This may partially be mediated by increases in local or systemic IL-1β with PSP pretreatment, thus effectively enhancing lymphocyte proliferation prior to tumor implantation." (PMID 28932226, 2017). "Moreover, treatment of the lung epithelial cell line A549 with IL-1β under normoxia was shown to induce a markedly increase in HIF-1α levels, which promotes tumor angiogenesis and invasion." (PMID 28927416, 2017). "Our working hypothesis is that within the aggressiveness niche, IL-1β secreted by metabolically stressed, hypoxic and inflamed IRISOE TNBC tumor cells recruits MSCs to the niche (step 1), and activates them to secrete CXCL1 (step 2)." (PMID 29262555, 2017). "Furthermore, co-treatment of tumor cells with TGF-β and TNF/IL-1β cytokines cooperatively stimulated expression of MMP9." (PMID 28423685, 2017). "Serum CCL2, IL-10, IL-5, IL-4, TNF-α, IL1-β and IL-12p70 levels increased with age irrespective of parity status, but were specifically reduced following OC tumor induction only in multiparous mice." (PMID 28966800, 2017). "As seen for inflammatory genes such as Il1b and Il6, also the expression of Trem1 was highly increased in Trem1+/+ tumors as opposed to matched tumor-free colonic mucosa." (PMID 29093489, 2017). "Addition of IL-1β NeuAb before MSCs contact (yellow bars), or CXCL1 NeuAb after MSCs (green bars) abrogated that increase in VEGF secretion from IRISOE tumor cells." (PMID 29262555, 2017). "The NGF antitumor mechanism may cause an increase of lymphocytic infiltration in the tumor, a rise in the levels of IL-1β and TNF-α in the serum of tumor-bearing mice, and an increase in aerobic glycolysis." (PMID 28878143, 2017). "Testing whether TGF-β and pro-inflammatory TNF/IL-1β cytokines cooperate in the regulation of MMP9, we found that MMP9 expression was induced only in tumor cells, while fibroblasts expressed high levels of MMP2." (PMID 28423685, 2017). "To investigate whether OPG indeed plays a role in IL1B tumor-promoting effects, we assessed the effects of OPG knockdown on IL1B-mediated cell invasion." (PMID 28143606, 2017). "The abscopal effects have been attributed to the induced inflammatory cytokines such as IL-1β, IL-6, and TNF-α released from the primary tumor site or non-tumor cells such as endothelial cells and cancer associated fibroblasts." (PMID 28977985, 2017). "Additionally, immunohistochemical tumor CRP expression and serum concentrations of interleukin (IL)-6 and IL-1β were measured." (PMID 28514756, 2017). "In addition, LCN2, which is involved in the cell differentiation and tumor invasion of ESCC, is up-regulated by IL-1β." (PMID 28410227, 2017). "Some reports suggest that CD11b+ Ly6G+ might accumulate in the liver due to tumor-derived inflammatory factors such as PGE2 of COX-2 origin, VEGF and IL-1β, released by LSECs after interacting with tumor cells via LFA-1/ICAM-1." (PMID 29207960, 2017). "As we have already identified IL1α, IL1β and GCLM as important transcriptional targets of glucose-induced H3 ubiquitination, we investigated whether they are involved in tumour sphere formation." (PMID 28300060, 2017). "Accordingly, high intratumoral levels of IL-1β were recently shown to activate endothelial cells to produce VEGF and IL-1β inhibition stably reduced tumor growth by limiting inflammation and inducing the maturation of immature myeloid cells into M1 macrophages." (PMID 28533483, 2017). "As expected, OT1 rejected EG7 tumours but not EL4 tumours, and IL-1β secretion was increased during OT1-mediated antigen-specific rejection of EG7 tumours." (PMID 28537251, 2017).
tumor (continued). "In the present study, the levels of TNF-α, IL1-β and IL12p70 increased in both aged groups irrespective of parity, and decreased as a response to tumor spread only in the parous group, in a similar fashion as observed for the M2-type cytokines." (PMID 28966800, 2017). "HMGB1 is a key mediator of chronic inflammation in MM, leading to Nalp3 inflammasome activation, macrophages accumulation, interleukin (IL)-1β and TNF-α secretion, and thus to activation of the NF-κB pathway, which increases cell survival and tumor growth after asbestos exposure." (PMID 27171110, 2016). "Besides, IL-1β, IP-10, M-CSF and TREM-1 levels in tumor tissues were also enhanced by LNT, further confirming the activated immune responses by LNT in mice." (PMID 27353254, 2016). "Moreover, embelin decreases the expression of cytokines such as IL-6, IL-1β and IL-17a, and reduces the infiltration of CD4+ T cells in the tumor stroma." (PMID 26799669, 2016). "The pro-inflammatory cytokines IL-1β, IL-6, IL-8, and VEGF promote tumor angiogenesis." (PMID 27171110, 2016). "Since IL-1β is critical for priming IFNγ-producing, tumor–antigen-specific CD8+ T cells, NDK from P. gingivalis could promote the immune evasion of tumor cells." (PMID 26788120, 2016). "IL-1β, IL-18, IL-6, IL-8 and TNF-α are produced by macrophages through the activation of toll-like receptor signaling, and their production is involved in the clearance of tumor cells by macrophages." (PMID 27671753, 2016). "We found that IL-1β induced CCL2 expression in macrophages and tumor cells." (PMID 27786298, 2016). "Previously, a variety of evidences revealed that pro-inflammatory cytokines, such as TNF-α, IL-1β, TGF-β, could induce metastasis of tumor cells via up-regulating chemokine receptors." (PMID 27356745, 2016). "Upstream regulators predicted to modulate expression and activity of the 240 upregulated expressed murine genes in the OS-2 tumor xenografts included the T-helper cell type-17 (Th17)-activating cytokines TGF-β (P-value 1.26E–27), IL-1β (P-value 9.07E–25) and IL-6 (P-value 9.03E–22)." (PMID 27874835, 2016). "The down-stream products of NF-κB: including COX-2, IL-6, IL-8, IL-1β are expressed at lower levels creating a tumour micro-environment that no longer facilitates progression or development of cancers." (PMID 27548217, 2016). "Our results show that IL-1β induced the expression of CCL2 in macrophages and tumor cells." (PMID 27786298, 2016). "Our results showed that miR-106a inhibition reduced IL-1β, IL-6, IL-8 and TGF-β production, indicating that miR-106a may contribute to tumor cell drug resistance by promoting the production of these cytokines." (PMID 25950430, 2015). "In tumor microenvironments, MSCs can be activated by pro-inflammatory cytokines IFN-γ, TNF-α, or IL-1β, which are secreted by tumor cells and macrophages and then produce immunomodulatory molecules, such as IDO, PGE2, IL-6, IL-10, HLA-G5, and nitric oxide (NO)." (PMID 26694366, 2015). "During the past few years, these activated tumor-associated fibroblasts have also been involved in the modulation of the antitumor immune response, especially by the secretion of soluble immunosuppressive factors in the tumor microenvironment (TGF-β, IL-1β, IL-6, and IL-10)." (PMID 26441986, 2015). "Pro-inflammatory molecules such as IL-1β, IL-6 and PGE2 are thought to promote the induction of MDSC in tumours, whereas pro-inflammatory TNF signalling can drive the accumulation of MDSC in tumours." (PMID 25738302, 2015). "Expression of IL-1β is increased in tumor and stromal cells in 90% of ER negative invasive breast carcinomas." (PMID 26106384, 2015). "In particular, proinflammatory cytokines, IL-1β, IL-6, and TNF-α may be released as part of the host response to the tumor or in response to tissue damage or depletion of immune cell subsets associated with cancer treatment." (PMID 25945105, 2015).
tumor (continued). "Accordingly, inhibition of COX-2 prior or during PDT with NSAIDs decreased tumor cell survival in a variety of (tumor) cell lines, which coincided with a reduction in levels of PGE2 and the proangiogenic factors MMP9, TNF-α, IL-1β, IL-10, and VEGF." (PMID 26516076, 2015). "IL1β significantly increased the percentage of SP cells in three independent tumor-derived primary cells in GSC-enriching medium, while no increase was observed in cells that were cultured in serum." (PMID 25987130, 2015). "Overall, a coordinated inflammatory network may be established at the tumor site between the cancer cells and stromal cells, set up by inflammatory cytokines such as TNF-α and IL-1β." (PMID 25928089, 2015). "On the other hand, elevated expression of IL-1β was observed in several of the negative tumor group." (PMID 26204886, 2015). "Data also show that this interaction is dependent on the nature rather than the type of tumor cells and that CDH1 and IL-1β expression by tumor cells are key factors in determining the outcome of hMSC–tumor cross-talk." (PMID 26204886, 2015). "Moreover, mRNA levels of inflammatory cytokines such as IL1β, IL6 and IL18 were found to be augmented in the tumor tissue after LTX-315 treatment." (PMID 26472184, 2015). "This TF induces tumour-promoting inflammation and activates pro-oncogenic pathways (in conjunction”with NF-kB and IL-6) and up-regulates many pro-inflammatory genes such as cyclooxygenase COX-2, IL-1b, IL-6, and IL-8." (PMID 25705130, 2015). "IL-1β is required for efficient priming of CD4+ T cells and interferone-γ (IFN-γ) producing tumor antigen-specific CD8+ CTLs and therefore for the generation of an anti-tumor immune response." (PMID 26500646, 2015). "Mechanistically, increased IL-1β within the tumor microenvironment leads to enhanced expression of cyclooxygenase-2 (COX-2), which contributes to the formation of early stage lesions and is a well-established tumor promoter." (PMID 26106384, 2015). "Microenvironment-derived IL-1β, rather than IL-1α, was found to be required for invasiveness and angiogenesis in different tumor cells." (PMID 24901233, 2014). "CAFs promote tumor growth and invasion secreting proangiogenic factors (i.e., VEGF-A and MMP-9), proinflammatory molecules (i.e., SDF-1, IL-6, and IL-1β), and several growth factors (i.e., TGF-β, platelet-derived growth factor, PDGF, and basic fibroblast growth factor, bFGF)." (PMID 25136593, 2014). "Although the induction of Tregs and Th17 could impair the immune response against tumor cells, it is reasonable to consider that the activation of Th1 and cytotoxic CD8 T cells by IL-1β and IL-18 may be beneficial to the host." (PMID 25071770, 2014). "For example, IL-1β, a special form of IL-1, can stimulate expression of VEGF and TNFα to promote tumor angiogenesis and adhesion molecules, including intercellular-adhesion molecule 1 (ICAM-1), vascular cell adhesion molecule 1 (VCAM-1) and E-selectin, to enhance invasion." (PMID 24338768, 2014). "The novelty of our study is that the combination of ALT-803 plus BCG stimulated the production of key sera and urinary cytokines (e.g., IL-1α, IL-1β and RANTES) leading to the activation and proliferation of NK cells, which led to the significant reduction in tumor burden." (PMID 24896845, 2014). "As results of tumor cell inoculation, marked decreases of spleen and submandibular lymph node weights, serum IFN-γ, splenic TNF-α, IL-1β and IL-10 contents, splenocytes and peritoneal NK cell activities were observed with histopathological atrophic changes of spleen and submandibular lymph nodes." (PMID 25477992, 2014). "On the contrary, gemcitabine administered mice showed significant (P < 0.05) decreases of the splenic TNF-α and IL-1β, and nonsignificant but dramatic decreases of splenic IL-10 contents as compared with tumor-bearing control mice, respectively." (PMID 25477992, 2014).